ALB (albumin)
Diseases named in the same sentence as ALB in open-access papers (continued):
Sharing a sentence is not in itself a finding about the gene and the disease.
diabetes (continued). "DKD was defined by diabetes, urine albumin to creatinine ratio (ACR) ≥ 30 mg/g and an estimated glomerular filtration rate (eGFR) < 60 mL/min/1.73 m2." (PMID 41377565, 2025). "This study confirms a relatively high incidence of OH in MHD patients and underscores that advanced age, diabetes, and low serum albumin levels are significant independent predictors of OH." (PMID 41281282, 2025). "Streptozotocin (STZ) administration elevated blood glucose and glycated albumin levels and altered lipid and renal function markers, confirming diabetes induction." (PMID 41614766, 2025). "The distribution of urine albumin levels among patients with diabetes revealed a predominant presence of microalbuminuria, with 156 (61.18%) falling into this category." (PMID 40734849, 2025). "Diabetes further reduces the efficiency of hepatocyte albumin synthesis, making NPAR a comprehensive indicator reflecting the “myocardial ischemia-hepatic inflammation-metabolic imbalance” pathological network." (PMID 40963676, 2025). "Significant risk factors for CIM in breast cancer patients undergoing chemotherapy included Age, BMI, Pathological staging, hemoglobin, Lymphocyte, Diabetes, Liver function, history of radiotherapy, chemotherapy regimen, genetic factors, albumin." (PMID 41438123, 2025). "Malnutrition, inflammation, diabetes, liver disease, and infection can reduce albumin production, thereby leading to hypoalbuminemia." (PMID 40809897, 2025). "This method effectively adjusted for the confounding effects of BMI, diabetes duration, serum albumin, triglyceride, and cardiovascular disease." (PMID 40123891, 2025). "Previous studies have identified several clinical indicators, such as age, pathology, history of diabetes, and initial T stage, along with biochemical markers including hemoglobin, albumin, and C-reactive protein, as independent predictors of PRNN." (PMID 41023922, 2025). "These factors—history of diabetes, type of chemotherapy, peripheral blood leukocyte count, and serum albumin level—were subsequently included in the multivariable logistic regression analysis." (PMID 39773012, 2025). "Eight independent predictors (sex, age, body mass index, alanine aminotransferase, albumin, diabetes duration, triglycerides, and high-density lipoprotein cholesterol) were included in the final model." (PMID 41459077, 2025). "To further strengthen our conclusions, we conducted a sensitivity analysis by incorporating age, diabetes, and albumin into the multivariable model, as suggested by reviewers." (PMID 41299285, 2025). "The included predictors were glomerulonephritis, diabetes, blood glucose, diastolic blood pressure, albumin-to-globulin ratio, P-CONUT, and age." (PMID 40403009, 2025). "The specific logistic regression model is as follows: logit (infection) ═ 4.6776 + 1.9990* History_of_Diabetes + 1.1949* Chemotherapy_types − 0.4493* WBC − 0.1637* albumin." (PMID 39773012, 2025). "These factors include a history of diabetes, type of chemotherapy administered, preoperative white blood cell count, and serum albumin levels." (PMID 39773012, 2025). "Fangchinoline, another major active component of S. tetrandra, effectively downregulates IL-6 and TNF-α levels by inhibiting p38 MAPK pathway activation, while improving the levels of GLU, Cr, ALB in STZ-induced diabetes rats." (PMID 41031161, 2025). "The variables included LVH, albumin, hemodiafiltration, age, dialysis age, activity and sun exposure, cerebral infarction, diabetes, CHD, hemoglobin, blood phosphorus, ejection fraction, vitamin D, calcium carbonate, and heart valve calcification." (PMID 40922290, 2025). "Predictors of complications included diabetes mellitus, advanced disease stage, higher American Society of Anesthesiologists (ASA) score, low preoperative hemoglobin, low serum albumin, longer operative time, and increased blood loss." (PMID 41280976, 2025).
diabetes (continued). "Patients with lower preoperative albumin levels were more likely to be smokers and to have comorbidities such as heart disease, hypertension, diabetes, stroke, renal disease, liver disease, and chronic obstructive pulmonary disease (COPD)." (PMID 41200138, 2025). "Study revealed that within the populations of diabetes and pre—diabetes, elevated blood glucose levels are capable of influencing the permeability of albumin and augmenting the excretion of urinary protein." (PMID 40271132, 2025). "According to some data, an increase in albumin excretion already within the normal range can predict the appearance of cardiovascular diseases in both diabetes and healthy individuals." (PMID 40414873, 2025). "Patients who developed MACEs were older and had higher prevalences of diabetes, hypertension, coronary disease, heart failure, and lower albumin/cholesterol." (PMID 41351012, 2025). "The high UAR population was characterized by elder, smoking, drinking, hypertension, hyperlipidemia, cardiac death, diabetes, and stroke, alongside higher creatinine, uric acid, and globulin levels, and lower albumin levels." (PMID 41305749, 2025). "The model predictors included history of diabetes and coronary heart disease; serous effusion; white blood cell; albumin-globulin ratio; left ventricular mass index, and age." (PMID 41084626, 2025). "This condition is associated with older age, lower albumin levels, lower body mass index (BMI), reduced hemoglobin levels, higher Nutritional Risk Screening (NRS) scores, and a higher prevalence of diabetes." (PMID 40538582, 2025). "Monitoring these biomarkers is critical for preventing or managing the adverse physiological effects of diabetes, and other emerging biomarkers like glycated albumin (GA) and methylglyoxal (MGO) are gaining attention." (PMID 40144552, 2025). "Having that in mind, it seemed relevant to examine the binding of antioxidants to albumin isolated from persons with diabetes, altered under pathophysiological terms and loaded with intrinsic ligands." (PMID 41321387, 2025). "High expression levels of miR-636 were noted during diabetes progression in rats’ renal tissues, in correlation with HbAc1 and the albumin creatinine ratio in urine." (PMID 40533788, 2025). "In addition, it is worth noting that some patients with diabetes may exhibit lower levels of lean mass, or reduced kidney function reflected by estimated glomerular filtration rate (eGFR) levels, or both, which are associated with lower albumin values." (PMID 40074368, 2025). "After 15 weeks of diabetes, urine albumin excretion increased approximately ten-fold in MRWT and MRMy mice." (PMID 41332229, 2025). "Significant predictors included age, smoking, diabetes, BMI, tumor location, lung metastasis, albumin (ALB) levels, and carcinoembryonic antigen (CEA) levels." (PMID 39895779, 2025). "These variables, encompassing diabetes duration, BMI, albumin, prealbumin, age, hemoglobin, temperature difference, and urinary incontinence, were integral in constructing a predictive nomogram." (PMID 40672825, 2025). "Their findings emphasize the importance of attributes such as blood pressure, hemoglobin, sodium, albumin, pus cell, red blood cell count, and diabetes mellitus for CKD prognosis and diagnosis." (PMID 39910170, 2025). "We used fasting blood sugar to screen patients for prediabetes and diabetes, and measured serum creatinine and urine albumin to creatinine ratio to diagnose chronic kidney disease (CKD)." (PMID 40747186, 2025). "Glomerulonephritis and diabetes were binary variables, while blood glucose, diastolic blood pressure, and albumin-to-globulin ratio were continuous variables." (PMID 40403009, 2025). "Medical records (age, gender, body mass index, smoking, drinking, hypertension, diabetes mellitus, lung diseases, blood transfusion, and serum albumin, lymphocyte, cholesterol levels) were collected." (PMID 41085005, 2025).
diabetes (continued). "After 4 months of treatment, the sulodexide group had a significant effect in reducing the albumin excretion rate in patients with type 1 and type 2 diabetes mellitus compared to the placebo group." (PMID 39975672, 2025). "Model 1 used sex, years since diabetes diagnosis, age, and BMI; Model 2 used albumin, HbA1c, PCA-derived inflammation score, CRP, and eGFR." (PMID 41226704, 2025). "The most common predictors included length of surgery, comorbid diabetes mellitus, serum albumin level, length of drain retention, and age." (PMID 41341393, 2025). "Subsequently, diabetes status and serum albumin levels were incorporated into multivariate logistic models alongside either serum tryptophan quartiles, kynurenine quartiles, or KTR quartiles." (PMID 41287688, 2025). "DN was defined as a urine albumin‐to‐creatinine ratio greater than 30 mg/g in individuals with diabetes." (PMID 40510788, 2025). "Among the models included in the 15 studies, the main predictors of diabetic retinopathy prediction models were diabetes duration, glycosylated hemoglobin, age, serum creatinine and urinary albumin creatinine ratio." (PMID 40717809, 2025). "For the full model: X = −30.1032 + (fasting glucose × 0.1578) + (BMI × 0.0943) + (log % glycated albumin × 3.7174) + (log adiponectin × −0.9768) + parental history of diabetes × 0.6662)) + (fasting triglycerides × 0.00317)." (PMID 40218874, 2025). "Glucose, body mass index (BMI), log adiponectin, % log glycated albumin, parental diabetes, TG, and the use of cholesterol-lowering medications entered the model (C statistic: 0.924; 0.898, biochemical variables: 0.898, and fasting glucose: only 0.876)." (PMID 40218874, 2025). "Multivariate logistic regression showed that declining kidney function was reliably predicted by nephrotic syndrome (Odds ratio (OR): 6.41, P = 0.004), serum albumin (OR: 0.31, P = 0.003), and diabetes mellitus (OR: 14.04, P < 0.001)." (PMID 39739269, 2025). "Cys C, Apo A, CRP, albumin, and GGT were identified as five potential biomarkers for evaluating the correlation between sleep score and the risk of diabetes complications." (PMID 40583046, 2025). "The main statistically significant factors were albumin levels below 3 g/dL (HR = 3.11, 95% CI—1.74–9.12, p = 0.01) and the presence of diabetes mellitus (HR = 1.98, 95% CI—1.05–5.22, p = 0.01)." (PMID 40095815, 2025). "By comparing the general conditions of the two groups of patients, there were statistically significant differences in BMI, diabetes, malnutrition status, albumin, calcium, phosphate, handgrip strength, and ASMI (p < 0.05)." (PMID 41225978, 2025). "Recent studies evaluated the prognostic significance of RDW to albumin ratio in aortic aneurysms, coronary artery disease, diabetes mellitus, cancer, stroke and other inflammatory diseases." (PMID 41011096, 2025). "End-to-side anastomosis, diabetes mellitus (DM), preoperative albumin (ALB) ≤ 33.6 g/L, drinking history and systemic inflammation response index (SIRI) > 1.18 were identified as independent risk factors for EJAL based on multivariable logistic regression." (PMID 40837566, 2025). "Serum zinc concentration was positively correlated with age (r = 0.273, P = 0.044), age at onset of diabetes (r = 0.316, P = 0.019), and serum albumin concentration (r = 0.294, P = 0.029)." (PMID 40382628, 2025). "On univariate analysis, diabetes mellitus, hypertension, serum albumin level, estimated glomerular filtration rate and the HALP score were found to be associated with in‐hospital mortality." (PMID 40022549, 2025). "For these reasons, diabetes practice guidelines recommend annual urine albumin-to-creatinine ratio and GFR tests, but early identification of high-risk patients remains challenging." (PMID 40142873, 2025).
diabetes (continued). "There wasn’t a noticeable variation in age, sex, hypertension history, diabetes history, coronary heart disease history, albumin level, prealbumin level, education level, smoking history, operation method and tumor stage in the CG (p > 0.05)." (PMID 40046912, 2025). "Independent variables included AST, platelet count, albumin, body weight, diabetes status, and race." (PMID 39057121, 2024). "Subgroup analyses were adjusted for covariates, including sex, age, WBC count, PLT, HGB, APTT, FIB, hypertension, diabetes status, trauma, urea, Crea, and ALB." (PMID 38606422, 2024). "HPLBII-P was significantly increased in patients with diabetes mellitus (p = 0.0008) and correlated to plasma glucose (r = 0.29, p = 0.001) and urine albumin concentrations (r = 0.55, p < 0.001)." (PMID 38731071, 2024). "The predictive nomogram encompassed seven pivotal variables: Activities of Daily Living (ADL), NIHSS score, diabetes, Body Mass Index (BMI), grip strength, serum albumin levels, and depression." (PMID 38761298, 2024). "The mentioned antioxidants have toxicity effects on human health via cyto/genotoxicity, interaction with albumin, and the initiation of inflammatory routes, metabolic disorders, augmented of diabetes." (PMID 39479655, 2024). "Age, BMI, diabetes, alcohol intake, physical activity, frailty, albumin, triglyceride, hsCRP, left ventricular ejection fraction (LVEF) and N-terminal pro-brain natriuretic peptide (NT-proBNP) among the three groups were statistically significant." (PMID 39478501, 2024). "It is worth mentioning that, given the obvious potential of serum albumin as a carrier system, there have been several clinically approved albumin-based formulations, such as for the treatment of cancer, hepatitis, and diabetes mellitus." (PMID 39458651, 2024). "Baseline age, BMI, duration of diabetes, HbA1c, eGFR, urinary protein excretion, hemoglobin, plasma albumin, insulin use, RAAS inhibitor use, statin use, and dyslipidemia were comparable in different groups." (PMID 39126619, 2024). "In a retrospective cohort study, patients aged > 40 years with T2D with serum creatinine and urine albumin measured from 2013 to 2019 were included from a multi-institutional diabetes registry." (PMID 38233790, 2024). "The main risk factors for a Dacron-cuffed CRI in hemodialysis were combined with diabetes, hemoglobin level, age, catheter indwelling time, serum albumin level, femoral vein catheter indwelling and catheterization times." (PMID 38589798, 2024). "A recent Japanese study assessing quality indicators in diabetes care showed that only 20% of the physicians regularly assessed urinary albumin levels, although regular checks for albuminuria are recommended in Japan." (PMID 37955878, 2024). "Multivariate analysis revealed that age, diabetes, total albumin, SII > 752.6 × 109 and a CRP > 20.25 mg/L were independent risk factors for POD patients." (PMID 38566241, 2024). "Age was negatively associated with serum albumin, calcium, phosphate, PTH, and creatinine and positively associated with diabetes, CVD, and dyslipidemia." (PMID 38820324, 2024). "Factors such as BMI ≥24 kg/m2, diabetes, preoperative low albumin levels, preoperative malnutrition, and surgical duration exceeding 3 h all demonstrated a significant increase in risk despite high heterogeneity." (PMID 39193402, 2024). "There were significant differences between the groups with and without gallstones in age, gender, race, alcohol consumption, smoking status, diabetes, hypertension, BMI, albumin, neutrophil counts, and lymphocyte counts." (PMID 39758317, 2024). "In recent years several studies aimed to investigate the biological effects of AGEs-RAGE in promoting invasion and metastasis of breast cancer, in patients with diabetes, by using methylglyoxal-derived bovine serum albumin AGEs (MG-BSA-AGEs)." (PMID 39830522, 2024).
diabetes (continued). "Age, diabetes prevalence, heart rate, systolic blood pressure, albumin level, and ejection fraction significantly differed among the three groups (P < 0.05)." (PMID 38229934, 2024). "To ascertain the mortality risk between pleural effusion groups, we calculated HRs for different subgroups such as age, sex, cardiovascular disease history, diabetes, tuberculosis history, BMI, albumin, EF, CRP, RRF, D/Pcr and Kt/Vure at baseline." (PMID 38241413, 2024). "According to the Kidney Disease: Improving Global Outcomes (KDIGO) guidelines, it is suggested that determining albumin excretion over a 24-h urine collection should be the initial method for screening kidney damage in patients with diabetes." (PMID 38962740, 2024). "Age, gender, race, education, DII, BMI, LSM, HSCRP, TC, HbA1c, ALT, AST, Albumin, minutes of sedentary activity, hypertension, diabetes, and use of drugs were all statistically different among the two groups (all p < 0.05)." (PMID 38559780, 2024). "In the anti-VEGF group, other baseline characteristics except for serum albumin, such as age, malignancy type, diabetes, infection, pemetrexed treatment or use of diuretics, were associated with sustained AKI." (PMID 38914959, 2024). "Older age, overweight or obesity, higher HbA1C and glycated albumin levels, higher LDL levels and hyperuricemia caused by IR most likely lead to MASLD in older patients with family history of diabetes and hypertension." (PMID 39618812, 2024). "This risk is intricately associated with various factors, including the capacity to perform daily activities (ADL), NIHSS scores, the presence of diabetes, BMI, grip strength, serum albumin, and depression." (PMID 38761298, 2024). "When comparing glycated albumin to HbA1c for diabetes control, a cross-sectional study has various limitations." (PMID 39231139, 2024). "Compared with higher serum albumin groups, patients in the lower quartiles were more likely to be older, female, suffer from diabetes and chronic heart disease at baseline, be less independent before onset, and suffer a more severe stroke." (PMID 38794724, 2024). "Patients with diabetes exhibited worse nutritional outcomes, with lower levels of albumin and prealbumin, higher MIS and SARC-F scores, and a higher prevalence of sarcopenic obesity compared to non-diabetic patients." (PMID 39337040, 2024). "For kidney failure, related morbidities (diabetes, cancer) and pathology results (albumin, creatinine, urea, activated partial thromboplastin time and haemoglobin) are also important." (PMID 38468330, 2024). "Patients with high ePWV were generally older, female, higher levels of neutrophil, platelet, BUN, albumin, serum podium, blood pH and bicarbonate, higher prevalence of heart failure, hypertension, diabetes, AF compared to the low group." (PMID 38357758, 2024). "Albumin is the most abundant protein found in the blood, and its presence in urine (albuminuria) is one of the earliest signs of kidney damage in diabetes." (PMID 38791060, 2024). "Univariate Cox regression analysis revealed that gender, serum albumin, serum phosphorus, diastolic BP, pulse pressure, DBPV, age, diabetes, ECW/TBW, and PA were associated with death." (PMID 38549547, 2024). "Unadjusted logistic regression analysis revealed that age, diabetes, lymphocyte count, total albumin, the SII and the CRP level were correlated with POD." (PMID 38566241, 2024). "Glycemic monitoring is an essential part of diabetes therapy, and glycated albumin (GA) and glycated haemoglobin (HbA1c) are two typical indicators." (PMID 39231139, 2024). "Recipients with varying degrees of liver disease severity had a comparable average age, proportion of hypertension and diabetes mellitus, and similar β-blocker usage and albumin levels." (PMID 38553611, 2024). "High body mass index (BMI), cervical anastomosis, diabetes mellitus, COPD, decreased postoperative albumin and postoperative renal dysfunction are potential risk factors for anastomotic leakage." (PMID 39416377, 2024).